ALDH1L1 (aldehyde dehydrogenase 1 family member L1)
Diseases named in the same sentence as ALDH1L1 in open-access papers (continued):
Sharing a sentence is not in itself a finding about the gene and the disease.
ovarian carcinoma (2 papers, 2023 to 2024). A malignant neoplasm originating from the surface ovarian epithelium. "Biomarkers such as RPL23, MRPS12, and ALDH1L1 have been used to predict the prognosis of ovarian cancer, but most studies focus on the prognostic role of a single biomarker." (PMID 39478854, 2024). "In the present study, RPL23, FGFR1OP2, CAPN10, ALDH1L1 and ACSM1 were significantly downregulated in ovarian cancer, while the up-regulation of RPL23, FGFR1OP2, CAPN10 and ALDH1L1 was associated with poor prognosis in patients with ovarian cancer." (PMID 39478854, 2024). "PKM2, MRPS12, NDUFC2, HPDL, MRPL14, COA6 and RNF144B were significantly upregulated in ovarian cancer tissues than in normal tissues (P < 0.05), while RPL23, FGFR1OP2, CAPN10, ALDH1L1 and ACSM1 were significantly down-regulated (P < 0.05)." (PMID 39478854, 2024).
adenoma (1 paper, 2016). A neoplasm arising from the epithelium. "Surprisingly, we also find that some stem cell-associated genes such as ALDH1L1 and CXCL1/3 are increased in the MDA34ad-TVA adenoma sample, suggesting a stem cell phenotype." (PMID 27100181, 2016).
astroblastoma (1 paper, 2023). "Other tumors also traditionally called astroblastomas more highly express OLIG2, GFAP, ALDH1L1, and S100 β astrocyte genes and exhibit histomorphologic and patient demographic characteristics more closely matching original descriptions of astroblastoma." (PMID 36604386, 2023).
bladder cancer (1 paper, 2022). "Future studies should test the role of ALDH1L1 in bladder cancer using animal models, as well as the responsiveness of ALDH1L1-proficient versus deficient tumors to chemotherapy." (PMID 36500483, 2022). "This also raises the question of whether ALDH1L1 can serve as a marker of bladder cancer aggressiveness." (PMID 36500483, 2022).
bladder urothelial carcinoma (1 paper, 2022). "These were additionally narrowed down, based on the similarity between the proteomic profiles and knowledge-based immuno-expression in bladder urothelial carcinoma (green heatmap); ALDH1L1, PKP2, and OGDH were excluded due to the discordancy." (PMID 35402263, 2022).
brain tumour (1 paper, 2025). "We detected the transfer of green mitochondria into the grafted mito:mKate2 cells in Aldh1l1:MitoTag mice, showing that astrocytes act as donors of mitochondria to GBM cells with compromised respiration in vivo, allowing for brain tumour onset and growth." (PMID 40325182, 2025).
breast tumors (1 paper, 2021). "ALDH1L1 is heterogeneously hypermethylated in many breast tumors, with high mRNA levels predicting favorable outcomes." (PMID 34068120, 2021). "However, ALDH1L1 is hypomethylated in breast tumors following chemotherapy, and may be important for tumor cell survival in response to metabolic stress." (PMID 34068120, 2021).
colon cancer (1 paper, 2022). "In colon cancer, ALDH1L1 expression is decreased and mRNA levels are negatively correlated with promoter hypermethylation." (PMID 35132081, 2022).
diffuse gastric adenocarcinoma (1 paper, 2016). An adenocarcinoma arising from the stomach. "Interestingly, for ALDH1A2, ALDH1A3 and ALDH1L1, high mRNA level was found to be significantly correlated to worsen OS in both gastric intestinal type adenocarcinoma and diffuse gastric adenocarcinoma, with the same trend as in all GC patients." (PMID 27015121, 2016).
ependymoma (1 paper, 2016). A WHO grade II, slow growing tumor of children and young adults, usually located intraventricularly. "Poor prognostic features were found in two other patients: low expression of PAX8, FHIT, CASP10, CHD2, with high expression of CHD11, FUS, and MTA1 in a patient with Ewing sarcoma, and gain of 1q and loss of 6q and overexpression of TNC, CALB1, PLAG1, ALDH1L1, and RELN in a patient with ependymoma." (PMID 28007021, 2016).
Gait ataxia (1 paper, 2025). A type of ataxia characterized by the impairment of the ability to coordinate the movements required for normal walking. "Our results indicate that astrocyte pathology has a minimal impact on the development of gait ataxia in VWM, with Gfap- and Aldh1l1-2b5ho mice developing a phenotype characterized by kyphosis, never reported in any previous VWM model and also not observed in VWM patients." (PMID 40326783, 2025).
gastric cancer (1 paper, 2018). A primary or metastatic malignant neoplasm involving the stomach. "ALDH1A3 and ALDH1L1 are found to be significantly correlated to the worsened overall survival for all patients with gastric cancer and are potential prognostic markers and therapeutic targets for patients with gastric cancer." (PMID 29416787, 2018).
glioma (1 paper, 2023). A benign or malignant brain and spinal cord tumor that arises from glial cells (astrocytes, oligodendrocytes, ependymal cells). "Moreover, a decrease in the protein ALDH1L1, which has been described as a marker of stemness in glioma models, was found." (PMID 37108181, 2023).
Gliosis (1 paper, 2020). Gliosis is the focal proliferation of glial cells in the central nervous system. "While GFAP and ALDH1L1, markers for astrocytes (and gliosis) were mostly detected in all specimens, the PDR samples showed greater number of GFAP positive cells present in the membrane as compared to MH and RD specimens." (PMID 32717933, 2020).
hemangioma (1 paper, 2018). A benign vascular lesion characterized by the formation of capillary-sized or cavernous vascular channels. "The findings that ALDH1L1 is highly expressed in regenerating liver, several transformed fibroblast cell lines and hemangioma, a benign tumor originated from endothelial cells, support the hypothesis that the ALDH1L1 antiproliferative effect is cancer specific." (PMID 29979702, 2018).
metastatic tumors (1 paper, 2024). "The upregulation of these two critical ovarian stem-cell markers CD44 and ALDH1L1 in omental metastatic tumors points to a potential interaction between the omental mesothelial cell niche and tumor-derived Notch-Jagged2 signaling in the development of CSC features by tumor cells." (PMID 38575576, 2024).
nasopharynx squamous cell carcinoma (1 paper, 2021). "Decreased levels of ALDH1A1, ALDH1A2, ALDH1A3, and ALDH1L1 expression were observed in 5 pairwise samples of nasopharynx squamous cell carcinoma (the results are not shown)." (PMID 34680942, 2021).
non-Hodgkin lymphoma (1 paper, 2019). Distinct from Hodgkin lymphoma both morphologically and biologically, non-Hodgkin lymphoma (NHL) is characterized by the absence of Reed-Sternberg cells, can occur at any age, and usually presents as a localized or generalized lymphadenopathy associated with fever and weight loss. "An elevated risk of non-Hodgkin lymphoma (NHL) was observed among carriers of the G allele at ALDH1L1 Ex21+31 (p.D793G; rs1127717)." (PMID 31737034, 2019).
oral squamous cell carcinoma (1 paper, 2023). "However, the specific role and mechanisms of ALDH1L1 in oral squamous cell carcinoma (OSCC) remainsobscure." (PMID 36336972, 2023).
pancreatic adenocarcinoma (1 paper, 2025). "Next, the expression of ALDH1L1, ALDH3A1, ALDH3B1, and ALDH5A1 in pancreatic adenocarcinoma (PAAD) samples was compared with that of matching TCGA and GTEx normal samples using GEPIA2." (PMID 40868269, 2025).
pancreatic cancer (1 paper, 2025). "ALDH3A1 and ALDH3B1 were found to be upregulated and ALDH1L1 downregulated in pancreatic cancer versus normal tissues." (PMID 40868269, 2025). "High expression of ALDH1L1, ALDH3A1, and ALDH3B1 was associated with shorter overall survival, while ALDH5A1 expression was associated with longer overall survival of pancreatic cancer patients." (PMID 40868269, 2025). "In this study comprehensively analyzed ALDHs in PAAD and identified four genes (ALDH1L1, ALDH3A1, ALDH3B1, ALDH5A1) as prognostic indicators for pancreatic cancer." (PMID 40868269, 2025). "ALDH1L1, ALDH3A1, ALDH3B1, and ALDH5A1 may serve as potential prognostic markers and predictors of chemotherapy response in pancreatic cancer patients." (PMID 40868269, 2025).
Pick disease (1 paper, 2024). A rare neurodegenerative disorder leading to dementia. "GFAP expression was increased in FTLD-tau (P = 0.0345) with the highest expression in Pick’s disease (P = 0.0019), while ALDH1L1 was unchanged." (PMID 37703311, 2024).
pilomyxoid astrocytoma (1 paper, 2009). An astrocytic tumor of uncertain relation to pilocytic astrocytoma. "A recent study employing gene expression profiling of NF1-associated and sporadic pilocytic and pilomyxoid astrocytomas identified aldehyde dehydrogenase 1 family member L1 (ALDH1L1) as an underexpressed candidate biomarker in more aggressive tumor subtypes." (PMID 19333441, 2009).
spina bifida (1 paper, 2022). A congenital neural tube defect in which vertebrae are not fully formed. "Our results further support this evidence as Sox9, Notch1, and BMP2/4 gene expression was upregulated at the time of early astrogliosis in spina bifida, and BMP2/4 expression with S100b and Aldh1l1, an early astrocyte markers." (PMID 35782393, 2022).
triple-negative breast carcinoma (1 paper, 2026). An invasive breast carcinoma which is negative for expression of estrogen receptor (ER), progesterone receptor (PR), and human epidermal growth factor receptor 2 (HER2). "Higher ALDH1L1 expression is associated with smaller tumor size, lower pT stage in luminal A and HER2+ subtypes, and lower nuclear grade in triple-negative breast cancer." (PMID 42266668, 2026).
cancer (41 papers, 2013 to 2026). A tumor composed of atypical neoplastic, often pleomorphic cells that invade other tissues. "An examination of these pathways has the potential to unveil the pivotal roles of these amino acids during this state of metabolic stress, and their implications in cancer formation following ALDH1L1 loss." (PMID 39728477, 2024). "In support of this function, loss of ALDH1L1 has been shown to accelerate the proliferation of cancer cells." (PMID 39728477, 2024). "This will aid in understanding the impact and relations of ALDH1L1 to cancer and other diseases linked to this enzyme." (PMID 39728477, 2024). "Aldehyde dehydrogenase 1 family member L1 (Aldh1l1or 10-formyltetrahydrofolate dehydrogenase) is a gene which encodes a protein that is known to regulate folate metabolism, cell motility, and cancer (Reviewed by Krupenko & Krupenko, 2018)." (PMID 37273576, 2023). "ALDH1L1 downregulation in cancers was linked to hypermethylation of the large CpG island in the gene promoter." (PMID 36500483, 2022). "The loss of ALDH1L1 protein positively correlates with the occurrence of malignant tumors, hence the suggestion that the enzyme is a putative tumor suppressor." (PMID 35629957, 2022). "We later established that silencing of the ALDH1L1 gene in several cancers and cancer cell lines (including A549 cells) is associated with strong methylation of the gene promoter." (PMID 33918472, 2021). "Regarding the role of the protein as a tumor suppressor, our cell culture studies demonstrated that forced expression of ALDH1L1 in ALDH1L1-deficient cancer cells produces strong antiproliferative effects, including cell cycle arrest and apoptosis." (PMID 34203215, 2021). "Alternative mRNA splicing of ALDH1L1 seem to be of clinical relevance as two ALDH1L1 variants were found to be expressed higher in either cancer or normal tissues." (PMID 34572930, 2021). "Meta-analysis results found that lower ALDH1A1 and ALDH1L1 expression was associated with poorer overall survival and poorer progression-free survival in cancer patients." (PMID 34680942, 2021). "The loss of ALDH1L1 protein positively correlates with the occurrence of malignant tumors and tumor aggressiveness, hence the enzyme is viewed as a candidate tumor suppressor." (PMID 31737034, 2019). "This review discusses the role of ALDH1L1 in folate metabolism and etiology of diseases with the focus on non-synonymous coding ALDH1L1 SNPs and their effects on the enzyme structure/function, metabolic role and association with cancer." (PMID 31737034, 2019). "Overall, the loss of ALDH1L1 protein positively correlates with the occurrence of malignant tumors and tumor aggressiveness [reviewed in], hence the suggestion that the enzyme is a candidate tumor suppressor." (PMID 31737034, 2019). "Several studies indicated that coding SNPs in ALDH1L1 are associated with altered risk of certain cancer types." (PMID 31737034, 2019). "Re-expression of the protein in ALDH1L1-deficient cancer cells inhibits proliferation and induces apoptosis, effects attributed to the decrease de novo purine biosynthesis." (PMID 29979702, 2018). "Furthermore, the expression of the enzyme in ALDH1L1-deficient cancer cells evokes an antiproliferative phenotype." (PMID 34203215, 2021). "The downregulation of ALDH1L1 expression is found in many cancer types, and the loss of the enzyme may confer a selective advantage for rapidly proliferating cells." (PMID 34203215, 2021). "The effects of these SNPs on the enzyme is not clear but studies indicate that some coding and non-coding ALDH1L1 SNPs are associated with altered risk of certain cancer types and it is also likely that specific haplotypes define the metabolic response to dietary folate." (PMID 31737034, 2019). "The downregulation of ALDH1L1 promotes malignant tumor growth, and silencing of ALDH1L1 is commonly observed in many cancers." (PMID 39728477, 2024).
cancer (continued). "Diminished expression of ALDH1L1 has been linked to poor prognosis in HCC, highlighting its critical role in cancer development and progression." (PMID 39728477, 2024). "Given the pivotal role of ALDH1L1 in cancer, it is crucial to delve into its relationship with specific metabolic pathways, particularly those related to serine and glycine, to understand the enzyme’s impact on cellular function." (PMID 39728477, 2024). "10‐formyltetrahydrofolate dehydrogenase (ALDH1L1) is a major folate enzyme, which is usually underexpressed in malignant tumors and competes with tumors for the same folate substrate." (PMID 36336972, 2023). "EPHX2, ACSF2, CYP27A1, ACSS1, and ALDH1L1 showed hypermethylation in several types of human cancer; on the contrary, AKR1B10, POLG2, NDUFB8, ACACB, and MRPS22 consistently showed hypomethylation in several types of human cancer." (PMID 37223030, 2023). "The results showed that compared with normal tissues, expressions of the ALDH1L1 gene are suppressed in early cancer stages, and are strongly inhibited in late cancer stages." (PMID 36336972, 2023). "Data indicate that the ALDH1L1 gene promoter is frequently hypermethylated in cancer, with low mRNA levels predicting poorer clinical outcomes." (PMID 36694633, 2023). "Natalia V reported that transient expression of ALDH1L1 suppresses cancer cell proliferation, resulting in cell death." (PMID 36336972, 2023). "Of note, expression of ALDH1L1 in cancer cell lines produces strong antiproliferative effects by activating specific apoptotic pathways." (PMID 35013550, 2022). "Numerous studies also demonstrated that ALDH1L1 is strongly and ubiquitously downregulated in different types of human cancers." (PMID 36500483, 2022). "Re-expression of ALDH1L1 through transient or induced stable transfection in cancer cells typically leads to inhibition of proliferation and the induction of apoptosis." (PMID 36500483, 2022). "Based on ubiquitous downregulation of ALDH1L1 in human cancers, the protein has been considered as a putative tumor suppressor." (PMID 36500483, 2022). "ALDH1L1 is considered as one of the major regulators of folate metabolism, the pathway which role in cancer was known for decades." (PMID 36500483, 2022). "Recent studies underscored ALDH1L1 as a candidate tumor suppressor and potential marker of aggressive cancers." (PMID 34928471, 2022). "Reports that ALDH1L1 protein is more strongly downregulated in advanced cancers are in agreement with the effect of the enzyme on proliferation rather than initiation." (PMID 34203215, 2021). "Cytosolic 10-formyltetrahydrofolate dehydrogenase (ALDH1L1) is commonly downregulated in human cancers through promoter methylation." (PMID 34203215, 2021). "GNMT is expressed at a low level in the majority of cancer cell lines and produces an antiproliferative effect, though to a lesser extent than does ALDH1L1." (PMID 34203215, 2021). "Another study highlighted the downregulation of ALDH1L1 as a part of a gene signature for late-stage compared to early-stage HCCs as well as for high-grade compared to low-grade cancers." (PMID 34203215, 2021). "Previously published studies have now shown that ALDH1L1 is universally and strongly downregulated in malignant tumors by its promoter methylation." (PMID 32528886, 2020). "ALDH1L1, cytosolic 10-formyltetrahydrofolate dehydrogenase, inhibited the invasion and migration of cancer cells via a specific folate-dependent mechanism." (PMID 32528886, 2020).